BTLA (B and T lymphocyte associated)
Diseases named in the same sentence as BTLA in open-access papers (continued):
Sharing a sentence is not in itself a finding about the gene and the disease.
psoriatic arthritis (1 paper, 2025). Joint inflammation associated with psoriasis. "A tendency for higher TIM3 expression in the group without psoriatic arthritis compared to the group with psoriatic arthritis (276.1 vs. 209.1 p = 0.0652), and, also, higher BTLA expression in the type I Ps group compared to the type II Ps group, were observed (24.19 vs. 15.70 p = 0.0365)." (PMID 40647414, 2025).
Sézary syndrome (1 paper, 2021). "Interestingly, non-clonal bystanders in Sézary syndrome have also been shown to have high BTLA expression that is sometimes even higher than Sézary cells." (PMID 34885092, 2021).
uveitis (1 paper, 2016). An inflammatory process affecting a part of or the entire uvea. "Whether BTLA participates in the pathogenesis of uveitis is unknown." (PMID 26841832, 2016).
vasculitis (1 paper, 2019). "However, we were focused on the role of BTLA in circulating T-cells to unravel whether this co-inhibitory pathway is in principle functional in ANCA-vasculitis." (PMID 31921121, 2019). "As the access to lesional T-cells is very limited in human disease and may not allow functional studies, the role of BTLA in regulating lesional T-cells could be addressed in future by employing one of the animal models available for ANCA-vasculitis." (PMID 31921121, 2019).
tumor (209 papers, 2011 to 2025). "This section explores the associations between BTLA and cancer progression, beginning with its relationship to tumor burden, invasiveness, and metastasis." (PMID 41471273, 2025). "Dysregulated BTLA expression has been associated with tumor immune evasion and poor prognosis in several cancers." (PMID 41471273, 2025). "BTLA is expressed at high levels on tumor-infiltrating Tregs, and its engagement has been associated with upregulation of FOXP3, CD25, and CTLA-4—hallmarks of highly suppressive Treg phenotypes." (PMID 41471273, 2025). "Increased BTLA expression on tumor-infiltrating T cells has been associated with lower event-free survival and treatment resistance." (PMID 41471273, 2025). "In tumors, similar to PD-1, BTLA dampens antitumor immunity, and high BTLA expression is frequently linked to T cell exhaustion in the tumor microenvironment." (PMID 41301417, 2025). "Meanwhile, the top three genes that are least correlated with KLF4 and associated with a tumor inhibitory effect in several tumors were BTLA, IDO1, and LAG3." (PMID 40299916, 2025). "Several studies have revealed a strong association between elevated BTLA expression and more aggressive tumor behavior in both solid and hematologic malignancies." (PMID 41471273, 2025). "In myeloid cells, BTLA signaling has been implicated in skewing macrophage polarization toward an M2-like, tumor-promoting phenotype." (PMID 41471273, 2025). "Upregulated BTLA expression is linked to impaired anti-tumor immunity and unfavorable disease outcomes." (PMID 38233898, 2024). "In the context of malignant tumors, upregulated BTLA expression is linked to the inhibition of anti-tumor immunity and inferior prognosis." (PMID 38928307, 2024). "BTLA expression on TILs has been frequently associated with impaired anti-tumor T-cell responses in several cancer subtypes." (PMID 37443727, 2023). "The connection between BTLA rs1982809 polymorphism and tumor susceptibility was evaluated in 6 case-control studies, including 3678 cases and 4866 controls." (PMID 35945755, 2022). "A recent study has confirmed that BTLA can inhibit T cell activity and facilitate tumor evasion, and high expression of BTLA is closely associated with poor prognosis in solid tumors." (PMID 35903713, 2022). "BTLA is found to be expressed in tumor-infiltrating lymphocytes (TILs) and is often associated with impaired anti-tumor immune response." (PMID 33859648, 2021). "BTLA promoter mutations clustered within a 27 bp region, and were associated with 5-fold reduced BTLA expression (PMann–Whitney = 0.056), the small number of tumours with expression data presumably preventing this relationship attaining significance." (PMID 34753926, 2021). "By analysing transcription factors (TFs) with evidence of BTLA promoter binding in ChIPseq, we found each variant tumour possessed a mutation predicted to disrupt TF binding, most frequently RUNX1/3, GATA3 and MYB." (PMID 34753926, 2021). "Tumor microenvironment analysis indicated BTLA was positively associated with the infiltrating levels of different immune cells and the activity of the anti-cancer immunity cycle." (PMID 33718105, 2020). "miR-149-3p, complementary to the 3′UTRs of mRNAs encoding PD-1, TIM-3, BTLA and Foxp1, was further confirmed to be downregulated in tumour-bearing mouse spleens." (PMID 31594465, 2019). "Our findings from the PyMT model suggested that high BTLA expression on NKT cells was associated with tumor development." (PMID 29518903, 2018). "Importantly, BTLA expression often adds independent prognostic value even when accounting for conventional clinical variables such as tumor stage, grade, or mutational status." (PMID 41471273, 2025). "The high-risk group was enriched in tumor progression pathways (like epithelial-mesenchymal transition, cell cycle checkpoints), exhibited low expression of immune checkpoint genes (BTLA, CD47), and showed increased sensitivity to cyclophosphamide and crizotinib." (PMID 40421217, 2025).
tumor (continued). "Tumor-associated BTLA+ B cells may adopt immunoregulatory phenotypes that dampen antitumor immunity." (PMID 41471273, 2025). "As a result, therapeutic interventions that indirectly enhance BTLA-HVEM inhibitory signalling—such as LIGHT blockade—may further diminish anti-tumour immune surveillance in an already at-risk population." (PMID 41030453, 2025). "This BTLA-mediated transition may facilitate tumor-associated macrophage reprogramming, contributing to immune tolerance and tumor progression." (PMID 41471273, 2025). "In addition, the overexpression in tumor cells of BTLA or BTLA together with PD-L1 is associated with a decrease in relapse-free and overall survival." (PMID 36140182, 2022). "Finally, 6 studies were identified to explore the relationship between the BTLA rs1982809 polymorphism and tumor risk." (PMID 35945755, 2022). "Others have shown that the HVEM‐BTLA pathway is also critical for maintaining DC homeostasis, suggesting that BTLA may limit not only the activation but also the expansion of tumor‐associated DC." (PMID 32508018, 2020). "Concerning the tremendous value of co‐signaling molecules in anti‐tumor therapy, and to better understand this issue, we conducted this case‐control study to clarify the detailed relationship of four tagging BTLA polymorphisms with the risk of ESCC in the eastern Chinese Han population." (PMID 32060969, 2020). "In CRC their expressions are strongly correlated with each other and, along with TIGIT and BTLA, are tightly associated with markers of T lymphocytes and cNK cells, in which they can inhibit receptor dependent activation, thereby dampening anti-tumor effector functions." (PMID 34975867, 2021). "As high-throughput sequencing and immune profiling technologies advance, BTLA expression patterns have been found to correlate not only with immune cell dysfunction but also with tumor aggressiveness, metastatic potential, and resistance to therapy." (PMID 41471273, 2025). "Collectively, these findings indicate that BTLA is not only a suppressor of anti-tumor immunity but also a marker of poor clinical prognosis across diverse malignancies." (PMID 41471273, 2025). "Despite significant advances in understanding the biology of B and T lymphocyte attenuator (BTLA) and its role in tumor immunology, the translation of BTLA-targeted strategies into clinical success remains in its early stages." (PMID 41471273, 2025). "Tumor-bearing mice were intraperitoneally injected with 15 mg/kg anti-BTLA mAbs, anti-PD-L1 mAbs or the isotype IgG control three times per week." (PMID 40463377, 2025). "Through its inhibitory signaling, BTLA not only dampens effector T cell function but also reinforces immunosuppressive networks dominated by Tregs, contributing to tumor immune evasion and resistance to immunotherapy." (PMID 41471273, 2025). "We then explore its role in facilitating tumor immune evasion, the crosstalk between BTLA and other immune checkpoints, and the specific effects of BTLA signaling on TILs and Tregs." (PMID 41471273, 2025). "Preclinical studies of tifcemalimab (anti-BTLA antibody) in combination with toripalimab (anti-PD-1 antibody) demonstrated synergistic anti-tumor effects." (PMID 40379637, 2025). "For example, in chronic lymphocytic leukemia, elevated BTLA expression on CD4+ and CD8+ T cells is associated with impaired T cell-mediated anti-tumor responses, leading to immune exhaustion." (PMID 40739089, 2025). "The expression levels of immune checkpoints, including BTLA, VTCN1, CD276, PDCD1, CD160, NRP2, and CD200, as well as the tumor-associated fibroblast marker FAP, were found to be higher in the high-risk group." (PMID 40364849, 2025). "Taken together, BTLA contributes to tumor immune evasion through multiple, overlapping strategies—by dampening effector responses, reinforcing suppressive immune populations, and enabling direct tumor-to-immune inhibitory signaling." (PMID 41471273, 2025).
tumor (continued). "These insights underscore the importance of further investigating BTLA as a functional contributor to tumor progression and as a possible therapeutic target to disrupt tumor-promoting immune pathways." (PMID 41471273, 2025). "Current BTLA-directed interventions face limitations in efficacy, patient selection, and safety, partly due to the heterogeneous expression of BTLA across tumor types and immune cell subsets, as well as the complexity of its bidirectional signaling with HVEM." (PMID 41471273, 2025). "This review provides a comprehensive overview of BTLA’s structure, signaling mechanisms, and functional implications in tumor immunity and discusses current advances and challenges in BTLA-targeted therapy." (PMID 41471273, 2025). "Within the tumour microenvironment, BTLA-HVEM signalling plays a critical role in suppressing anti-tumour immunity: HVEM expressed by tumour or stromal cells engages BTLA on T cells, driving T cell exhaustion." (PMID 41030453, 2025). "Preclinical studies demonstrate that BTLA blockade—alone or combined with PD-1 inhibition—revives effector function and enhances tumor control." (PMID 41471273, 2025). "Integration of genomic, transcriptomic, and proteomic profiling can identify patients whose tumor immune landscapes are particularly dependent on BTLA-mediated suppression." (PMID 41471273, 2025). "We found that 24 h after two rounds of antibody administration, the combination of anti-BTLA and anti-PD-L1 mAbs significantly increased the tumor infiltration of CD8+ and CD4+ T cells compared to that in the other groups." (PMID 40463377, 2025). "The combination of anti-PD-L1 and anti-BTLA significantly inhibited tumor growth and extended the survival of tumor-bearing mice." (PMID 40463377, 2025). "PBMCs combined with anti-BTLA plus anti-CTLA-4 or anti-PD-1 Ab had significant tumor-killing ability in vitro." (PMID 41011166, 2025). "Compared to tumors with diploid/normal copy number, levels of B cell and CD4+ T cell infiltration were reduced in tumor samples with arm-level deletion of BTLA, CLDN11, and FGF5." (PMID 39796775, 2025). "In this current study, PBMCs combined with anti-BTLA plus anti-CTLA-4 or anti-PD-1 Ab had significant tumor-killing effects on the PTX-pretreated tumor cells through activation of T cells by the BTLA blockade." (PMID 41011166, 2025). "This dual benefit—simultaneous suppression of immune attack and enhancement of tumor cell viability—further positions BTLA as a critical immune checkpoint in cancer biology." (PMID 41471273, 2025). "In advanced stages, sustained BTLA–HVEM signaling has been correlated with impaired anti-tumor immunity and poor clinical prognosis in several malignancies." (PMID 41471273, 2025). "We evaluated the effects of the combination of anti-BTLA and anti-PD-L1 mAbs on tumor growth and overall survival of mice." (PMID 40463377, 2025). "BTLA also participates in immune exclusion, a phenomenon wherein effector immune cells are physically or functionally prevented from infiltrating tumor cores." (PMID 41471273, 2025). "CD8+ T cells from tumor-bearing mice administered anti-PD-L1 and anti-BTLA blockade agents exhibited increased cytotoxicity and proliferation." (PMID 40463377, 2025). "In contrast to PD-1 or CTLA-4, BTLA forms a bidirectional signaling axis with its ligand, influencing not only T cells but also tumor cells and APCs." (PMID 41471273, 2025). "BTLA has emerged as a critical immune checkpoint in tumor immunology, functioning as a key regulator of immune homeostasis within the tumor microenvironment." (PMID 41471273, 2025). "While the HVEM/LIGHT pathway enhances the eradication of tumors, the binding of HVEM to BTLA, which is predominantly expressed in tumor-specific T-cells, suppresses the response of CD8+ T-cells and thus promotes immune evasion." (PMID 40243455, 2025).
tumor (continued). "A similar phenomenon is observed in lung cancer and melanoma, where BTLA is overexpressed on tumor-infiltrating T cells, impairing their cytotoxic function." (PMID 40574024, 2025). "Given the complexity of the TME, where diverse immune cell types contribute to tumor control or progression, understanding BTLA’s functions outside of T cells is crucial for developing more comprehensive therapeutic strategies." (PMID 41471273, 2025). "We further analyzed the effect of combined anti-BTLA and anti-PD-L1 mAbs on lymphocyte function in tumor immune microenvironment." (PMID 40463377, 2025). "Taken together, BTLA is broadly expressed in tumor-infiltrating immune populations across multiple cancer types." (PMID 41471273, 2025). "In this study, we characterized BTLA expression in lymphocytes isolated from malignant pleural effusion fluid, tumor tissue and peripheral blood of NSCLC patients." (PMID 40463377, 2025). "Several elevated ligand-receptor pairs in CML were related to cancer development, such as ADRB2_VEGFB, which was involved in tumor angiogenesis, and BTLA_TNFRSF14, which was reported in immune regulation." (PMID 40612663, 2025). "In this study, we examined BTLA expression during treatment in a mouse model of LLC tumor burden that is insensitive to PD-1/PD-L1 blockade treatment." (PMID 40463377, 2025). "Ultimately, successful BTLA-targeted immunotherapy will likely require a tailored approach, combining BTLA modulation with other ICIs, targeted therapies, or immunomodulators based on each patient’s tumor biology and immune status." (PMID 41471273, 2025). "One major challenge is the variability of BTLA expression across tumor types, immune cell subsets, and even among patients with the same cancer." (PMID 41471273, 2025). "BTLA is highly expressed on tumor-specific T cells in cancer patients, and its upregulation in several TILs is associated with poor prognosis." (PMID 40463377, 2025). "The inhibitory signaling of BTLA dampens antitumor immunity and supports a microenvironment conducive to tumor cell invasion, migration, and distant colonization." (PMID 41471273, 2025). "Blocking or deleting BTLA enhances T cell cytotoxicity and tumor clearance in preclinical models, underscoring its therapeutic potential." (PMID 41471273, 2025). "In murine tumor models, BTLA+ Tregs exhibit greater suppressive capacity than their BTLA− counterparts, suppressing CD8+ T cell proliferation and cytokine production more effectively." (PMID 41471273, 2025). "Expression of inhibitory receptors (IRs) PD-1, TIM-3 (HAVCR2), and BTLA was significantly higher on CD8+ T cells isolated from tumor microenvironment, which is the major feature of exhaustive T cells." (PMID 38366083, 2024). "The monocyte can be considered a maestro within the TME in both solid tumors and hematologic malignancies, moreover, the applications of checkpoint inhibitors, such as PD-1, CTLA-4, and BTLA, have emerged as a new upsurge of tumor immunotherapy." (PMID 38742110, 2024). "BTLA has been shown to be upregulated in T cell-infiltrating tumors and taking part in suppressing anti-tumor immune responses." (PMID 38254772, 2024). "We found that it was correlated with tumor immunotherapy targets BTLA, CTLA4, HAVCR2, LAG3, PDCD1, and TIGIT in HNSC; ICOS were all significantly correlated." (PMID 39483471, 2024). "Among them, 41.9% displayed high BTLA levels which correlated with tumor location and shorter patient OS." (PMID 38233898, 2024). "BTLA blockade has been shown to limit tumour growth and improve survival in a murine model and it is a target in clinical trials." (PMID 39471840, 2024). "HVEM is believed to be an element of tumor immune evasion, as its strong expression on malignant cells can mediate functional inhibition of BTLA+ T cells." (PMID 38835768, 2024). "In another phase I/II clinical trial (NCT05000684), safety and anti-tumor activity of tifcemalimab (anti-BTLA) in combination with toripalimab treatment were evaluated." (PMID 38233898, 2024).